CEP97 (centrosomal protein 97)
Description:
Acts as a key negative regulator of ciliogenesis in collaboration with CCP110 by capping the mother centriole thereby preventing cilia formation. Required for recruitment of CCP110 to the centrosome.
Synonyms: LRRIQ2; FLJ23047; 2810403B08Rik
Tractability: PROTAC: ubiquitination databases record sites on it; its protein half-life has been measured.
Gene: Protein-coding gene on chromosome 3 (101,724,534 to 101,770,562, forward strand). Ensembl gene ENSG00000182504.
Subcellular location: Cytoplasm, cytoskeleton, microtubule organizing center, centrosome; Cytoplasm, cytoskeleton, microtubule organizing center, centrosome, centriole
Subcellular location (Human Protein Atlas): Centriolar satellite; Centrosome; Cytosol; Basal body
Pathways (Reactome):
Organelle biogenesis and maintenance: Anchoring of the basal body to the plasma membrane
Signal Transduction: RHOV GTPase cycle
Gene Ontology:
Molecular function: protein binding; protein-macromolecule adaptor activity
Biological process: negative regulation of cilium assembly; regulation of mitotic spindle assembly
Cellular component: centriole; centrosome; protein-containing complex; cytosol
Genetic constraint (gnomAD): Loss-of-function variants: 34 observed, 53.41 expected, observed/expected ratio (o/e) 0.64, 90% interval 0.48 to 0.85. The upper end of that interval is the gene's LOEUF score, 0.85, which puts it in group 3 of 6, group 1 being the genes least tolerant of losing a copy. Missense variants: 774 observed, 887.99 expected, observed/expected ratio (o/e) 0.87, 90% interval 0.82 to 0.93. Synonymous variants: 284 observed, 329.4 expected, observed/expected ratio (o/e) 0.86, 90% interval 0.78 to 0.95.
Homologues: Orthologues: chimpanzee CEP97 (99% identical), macaque CEP97 (94% identical), dog CEP97 (87% identical), rabbit CEP97 (84% identical), pig CEP97 (83% identical), guinea pig CEP97 (81% identical), rat Cep97 (77% identical), mouse Cep97 (77% identical), tropical clawed frog cep97 (50% identical), zebrafish cep97 (32% identical), Drosophila melanogaster Cep97 (27% identical), Caenorhabditis elegans T05H4.3 (11% identical). Paralogues in human: LRRC9 (15% identical), LRRCC1 (12% identical), DNAAF11 (11% identical), LRGUK (11% identical), DNAAF1 (10% identical), DRC3 (10% identical), LRRC43 (10% identical), LRRIQ3 (10% identical), LRRC46 (8% identical), LRRC49 (8% identical), LRRC23 (8% identical), LRRC61 (7% identical), and 1 more.
Diseases named in the same sentence as CEP97 in open-access papers:
CEP97 is named in the same sentence as 7 diseases in open-access papers, as found by Europe PMC text mining. Sharing a sentence is not in itself a finding about the gene and the disease. The quoted sentences say what the papers report.
ciliopathy (2 papers, 2022 to 2023). A genetic disorder of the cellular cilia or the cilia anchoring structures, the basal bodies, or of ciliary function. "Our findings on the collaborative role of CEP97 and Dyrk1a in multiciliation may add to our existing knowledge regarding pericentrin overexpression in patients with trisomy 21 and therapeutic approaches for the respiratory diseases in patients with ciliopathy and Down syndrome." (PMID 34787650, 2022).
COVID-19 (1 paper, 2021). A disease caused by infection with severe acute respiratory syndrome coronavirus 2. "Four genes near our chromosome 3 locus—NXPE3, ZBTB11, CEP97, and RPL24I—have been linked to COVID-19 SNPs in HGI (COVID-19 Host Genetics Initiative, 2021) and studies based on HGI data." (PMID 35222515, 2021). "Gene-based analyses identified five significant gene associations with COVID-19 positivity on chromosome 3 (p < 0.05/19,148 genes = 2.6 × 10−06): NXPE3 (p = 1.6 × 10−11), ZBTB11 (p = 5.8 × 10−11), CEP97 (p = 1.0 × 10−10), RPL24I (p = 9.4 × 10−09), and PCNP (p = 6.8 × 10−07)." (PMID 35222515, 2021).
CEP97 also shares sentences with these, for which no sentence is quoted: retinal degeneration (2 papers); Down syndrome (1); hydrocephaly (1); respiratory diseases (1); trisomy 21 (1).